ARID3C (AT-rich interaction domain 3C)
Description:
Transcription factor involved in monocyte-to-macrophage differentiation. Forms a complex with NPM1 to translocate to the nucleus, acting as a transcription factor that promotes the expression of the genes involved in macrophage differentiation, such as STAT3, STAT1 and JUNB.
Tractability: No criterion of Open Targets' tractability assessment is met for any kind of drug.
Gene: Protein-coding gene on chromosome 9 (34,621,049 to 34,629,066, reverse strand). Ensembl gene ENSG00000205143.
Subcellular location: Nucleus
Gene Ontology:
Molecular function: DNA-binding transcription factor activity, RNA polymerase II-specific; protein binding; chromatin binding; DNA binding
Biological process: macrophage differentiation; regulation of transcription by RNA polymerase II
Cellular component: membrane raft; nucleus; cytoplasm
Genetic constraint (gnomAD): Loss-of-function variants: 42 observed, 31.53 expected, observed/expected ratio (o/e) 1.33, 90% interval 1.04 to 1.72. The upper end of that interval is the gene's LOEUF score, 1.72, which puts it in group 6 of 6, group 1 being the genes least tolerant of losing a copy. Missense variants: 581 observed, 502.89 expected, observed/expected ratio (o/e) 1.16, 90% interval 1.08 to 1.24. Synonymous variants: 213 observed, 210.44 expected, observed/expected ratio (o/e) 1.01, 90% interval 0.9 to 1.13.
Homologues: Orthologues: chimpanzee ARID3C (99% identical), macaque ARID3C (94% identical), dog ARID3C (88% identical), pig ARID3C (88% identical), rabbit ARID3C (86% identical), mouse Arid3c (85% identical), rat Arid3c (85% identical), guinea pig ARID3C (85% identical), zebrafish arid3c (52% identical), tropical clawed frog arid3c (49% identical), Drosophila melanogaster retn (40% identical), Caenorhabditis elegans cfi-1 (33% identical). Paralogues in human: ARID3A (49% identical), ARID3B (46% identical).
Diseases named in the same sentence as ARID3C in open-access papers:
ARID3C is named in the same sentence as 5 diseases in open-access papers, as found by Europe PMC text mining. Sharing a sentence is not in itself a finding about the gene and the disease. The quoted sentences say what the papers report.
ovarian carcinoma (2 papers, 2021 to 2022). A malignant neoplasm originating from the surface ovarian epithelium. "ARID3C has been identified as one of the main downstream targets of β-catenin, and ARID3C knockdown could inhibit cell proliferation of ovarian cancer." (PMID 36034939, 2022). "While far less is known about ARID3C, RNA-Seq analyses recently identified it within a signaling complex consisting of protein tyrosine phosphatase receptor type R (PTPRR), α-catenin, β-catenin, and E-cadherin that form exclusively in ovarian cancer." (PMID 33804610, 2021).
breast carcinoma (1 paper, 2021). "The expression of ARID1A, ARID1B, ARID2, ARID3A, ARID4A, and ARID4B in no-luminal subtypes was lower than luminal subtypes, however, ARID3C, ARID5A, and JARID2 mRNA expression were higher in no-luminal subtypes of breast cancer tissues." (PMID 33592583, 2021).
hepatocellular carcinoma (1 paper, 2023). A malignant tumor that arises from hepatocytes. "High ARID3C expression reduced the survival of hepatocellular carcinoma patients, and the ARID family of genes are known to contribute to the development of tumors." (PMID 36999961, 2023).
cancer (4 papers, 2021 to 2022). A tumor composed of atypical neoplastic, often pleomorphic cells that invade other tissues. "Indicating that ARID3C could modulate IgH activity to enhance immune response and improve the prognosis of cancers." (PMID 34149794, 2021). "ARID3C had notable differential expression between tumour and normal tissues in CHOL, and our immune analysis showed that ARID3C expression was negatively associated with immune score in this type of cancer." (PMID 35127746, 2021). "The genes—including BEST4, LMO1, ARID3C, TMEM44, FKBP10, and TRIB3—were correlated with VSX1 and might play a primary role in the transcriptional misregulation of cancer from the TCGA database." (PMID 36463181, 2022). "Concerning ARID3C and ARID5A, there were no studies carried on the relationship between them and cancers as yet." (PMID 33592583, 2021).
tumor (2 papers, 2021). "The expressions of ARID1A, ARID2, ARID3C, JARID1C and JARID2 were strongly correlated with tumour stage." (PMID 35127746, 2021). "The mRNA expression of ARID3A, ARID3B, ARID4B, JARID1B, JARID1C, JARID2 in tumor tissues was more expressive in normal tissues, ARID1B, ARID3C, ARID4A, ARID5A, ARID5B, JARID1A mRNA expression in tumor tissues were lower than that in the normal tissues (p<0.05)." (PMID 33592583, 2021). "In our study, expression of ARID3C and ARID5A were lower in tumor tissues than in normal tissues." (PMID 33592583, 2021).